IL6 (interleukin 6)
Diseases named in the same sentence as IL6 in open-access papers (continued):
Sharing a sentence is not in itself a finding about the gene and the disease.
food allergy (22 papers, 2009 to 2025). Gastrointestinal disturbances, skin eruptions, or shock due to allergic reactions to allergens in food. "This dual role of IL-6 in both autoinflammatory and allergic pathways provides a compelling rationale for investigating the potential impact of IL-6 inhibition on food allergy outcomes, as illustrated in this case report." (PMID 40130131, 2025). "The unexpected resolution of food allergies in this patient following treatment with tocilizumab highlights the potential dual role of IL-6 inhibition in modulating both autoimmune and allergic pathways." (PMID 40130131, 2025). "IL-6 promotes Th2 differentiation, enhances IgE production, and contributes to mast cell activation, all of which are central to developing IgE-mediated food allergies." (PMID 40130131, 2025). "This case report presents a novel observation of concurrent remission of systemic JIA and IgE-mediated food allergies following IL-6 blockade with Tocilizumab." (PMID 40130131, 2025). "S100A8/A9 and inflammatory-related factors, including TLR4, NF-κB, TNF-α, IL-6 and IL-1β, is closely related to food allergies." (PMID 33499808, 2021). "In our study, we also observed significant decreases in DNAm levels for the gene IL1B and IL6 in PA compared with NA individuals, suggesting a link between epigenetic regulation of the innate immune system and food allergy." (PMID 33571165, 2021). "In fact, the strong Th2 adjuvant cholera toxin (CT), commonly used to induce food allergy in mouse models, enhances the expression of Cldn2, Muc2, Il17, and Il6 in the small intestine when administered with food proteins to produce sensitization." (PMID 34684302, 2021). "The mRNA expression levels of the cytokines IL-4 and IL-6 were significantly increased in the jejunum of the food allergy animals (P = 0.002 and P = 0.005, respectively)." (PMID 19450258, 2009). "This variety in receptor expression suggests mast cells respond differently, such as in the gut where immunosuppressive IL-10 stimulates the development of food allergy or in the lungs where transforming growth factor-β1 (TGF-β1) can enhance mast cell IL-6 production." (PMID 32098318, 2020). "We have also previously reported that the non-T cell fraction from food allergic infants showed increased inflammatory cytokine responses (TNFα, IL-6, IL-1β, and IL-8) to LPS stimulation, and that this was more pronounced in infants with persistent food allergy outcomes." (PMID 33072108, 2020). "In food allergies, bile acids inhibit NF-κB activation by activating FXR, thereby reducing the production of pro-inflammatory cytokines such as TNF-α, IL-6, and IL-1β." (PMID 40735411, 2025). "It has been reported that RA increases the expression of anti-inflammatory cytokines IL-6 and FOXP3 and increases the expression of pro-inflammatory cytokines in rats, in which a food allergy model was created with ovalbumin." (PMID 39770446, 2024). "In cord blood, infants who developed food allergies showed a higher ratio of monocyte/CD4+ T cells, which would secrete higher amounts of inflammatory cytokines, such as IL-1β, IL-6, and TNF-α that further suppressed IL-2 expression by CD4+ T cells." (PMID 38263182, 2024). "A study demonstrated that only the level of TNF-α was increasing in the cerebral cortex of food allergy mice; the levels of IL-1β and IL-6 were not changed." (PMID 40429903, 2025). "In this mouse model of food allergy, we demonstrated a decreased response to a muscarinic agonist, and increased levels of proinflammatory IL-6 and Th2-related IL-4, but not Th1-related IFN-γ mRNAs in jejunum." (PMID 19450258, 2009).
Graves disease (22 papers, 2006 to 2026). Graves' disease is an autoimmune disorder that leads to overactivity of the thyroid gland (hyperthyroidism).It is caused by an abnormal immune system response that causes the thyroid gland to produce too much thyroid hormones. "SARS-CoV-2 infection leads to increased IL-6 and Th1 cytokines, whereas autoimmune response in Graves’ disease is mainly associated with Th2 cells." (PMID 35495619, 2022). "IL-6 plays diverse roles in normal and disease-associated immunity such as that associated with Graves’ disease (GD)." (PMID 24086448, 2013). "IL-6 plays an important role in the pathogenesis of Graves' disease and its orbital component, thyroid-associated ophthalmopathy (TAO)." (PMID 21209948, 2010). "Serum IL6 levels correlate with disease activity, reinforcing its role as a key mediator in Graves’ disease." (PMID 41155084, 2025). "Serum cytokine levels (including IL-6, IL-9, IL-17A, IL-17F, and IL-22) exhibited significant differences between healthy subjects and patients with newly diagnosed hyperthyroid Graves’ disease (GD) under varying serum iodine concentration (SIC)." (PMID 40895623, 2025). "Genotypic frequencies and association given by the odds ratio (OR) and 95% confidence intervals (95% CI) between genetic variants in IL1B, TNFA, IL6, and IFNGR1, and Graves' disease and Hashimoto's thyroiditis." (PMID 25127106, 2014). "For example, stimulated fibroblasts secrete multiple cytokines, including IL-6, which stimulates B cell differentiation and thus Graves' disease IgG." (PMID 22039452, 2011). "It has been shown that pro-inflammatory cytokine interleukin 6 (IL-6) is one of the main triggers for increased hepcidin expression, and increased IL-6 serum levels are observed in hyperthyroid human patients with both Graves’ disease and toxic adenoma." (PMID 39518858, 2024). "Cytokines are elevated in autoimmune (i.e., IL-18, IL-6) and non-autoimmune hyperthyroidism (i.e., TNF-α, IL-8, IL-6), and this could be associated with the chronic effects of thyroid hormone increase." (PMID 33935970, 2021). "IL-6 and TNFα are both increased in Grave's disease (hyperthyroid state), however since these cytokines have been reported to decrease adiponectin and increase C3, this cannot explain the demonstrated increase in adiponectin and decrease in C3 in the hyperthyroid state in the present study." (PMID 16472384, 2006). "Collectively, it is hypothesized that if the anti-FSC antibody has a stimulating ability to promote IL-6 or CXCL10 secretion from FSCs like TSH receptor antibody does in Graves’ disease, a functional impairment of corticotroph may occur, resulting in acquired IAD." (PMID 33679614, 2021). "Polymorphisms in the IL6-174 G/C (rs1800795), TNFA-308 G/A (rs1800629), IL1B-511 C/T (rs16944), and IFNGR1-56 T/C (rs2234711) genes were assessed in a case-control study comprising 420 Hashimoto's thyroiditis patients, 111 Graves' disease patients and 735 unrelated controls from Portugal." (PMID 25127106, 2014).
IgA nephropathy (22 papers, 2014 to 2025). "IL-6 has been studied as disease activity marker in IgA nephropathy, being associated since very long with proteinuria worsening." (PMID 34205600, 2021). "The assessment of the relations between glycoconjugates/antigangliosides and disease activity markers in IgA nephropathy group showed a positive correlation between IL-6 and TSA (r = 0.39, p = 0.028), respectively orosomucoids (r = 0.28, p = 0.041)." (PMID 34205600, 2021). "The present study evaluated IL-6 profile in IgA nephropathy and assessed higher levels of IL-6, sIL-6R and sIL-6R/sgp 130 compared with control group, but significant lower than in LN, respectively lower sgp 130 than in control group, but higher than in LN." (PMID 34205600, 2021). "Of these proinflammatory cytokines, interleukin-6 (IL-6) overexpression has been detected in kidney biopsies and in the urine of patients with IgA nephropathy." (PMID 35046941, 2021). "In IgA nephropathy, the mesangial deposited molecular polymeric IgA1 and complement component can promote secretion of IL-6, and though its serum and urine levels are elevated and correlated with disease evolution." (PMID 34205600, 2021). "Urinary IL-6 has been identified as a marker of renal IL-6 production: high levels of it arise in 30-50% of IgA nephropathy cases." (PMID 25520922, 2014). "Our previous studies demonstrated the role of IL‐6 in an animal model of IgA nephropathy." (PMID 39945225, 2025). "This case as well as other reports suggest that overproduction of IL-6 may also induce IgA vasculitis, including IgA nephropathy." (PMID 39776937, 2024). "TNF-α and IL-6 are both common proinflammatory factors in IgA nephropathy." (PMID 36865740, 2023). "The pathogenesis of IgA nephropathy (IgAN) is still unknown, but reportedly, interleukin 6 (IL-6) is involved in this process." (PMID 35870042, 2022). "Low IL-6 levels were found in patients with IgA nephropathy." (PMID 30608959, 2019). "The n-3 PUFA (DHA+EPA) concentration used here, 35.4 g/kg, was selected because this approximate level has been previously demonstrated to be efficacious by our laboratory for ameliorating both deoxynivalenol-induced IgA nephropathy and ex vivo IL-6 expression." (PMID 24945254, 2014). "Three of the twenty-one patients developed progressive IgA nephropathy disease, which correlated with very high urinary IL-6 levels, suggesting that determination of urinary IL-6 concentrations may serve as a prognostic factor for the development of IgA nephropathy." (PMID 37189804, 2023). "The CP improved kidney inflammation and fibrosis in IgA nephropathy rat models by reducing MCP-1, TNF-α, IL-1β, and IL-6 levels." (PMID 33806085, 2021). "IgG-ddIgA1 complexes from both patients with IgA nephropathy (IgAN-IgG-ddIgA1) and healthy controls (HC-IgG-ddIgA1) could induce the proliferation of mesangial cells and up-regulate the expression of multiple inflammatory cytokines, including IL-6, MCP-1 and CXCL1." (PMID 28969604, 2017). "For example, in IgA nephropathy, glomerular fibrosis results from IgA activation of mesangial cells to secrete TNF-α, IL-6 and TGF-β and in patients with IgA nephropathy, significantly reduced levels of glomerular BMP-7 were demonstrated in renal biopsy samples." (PMID 37626268, 2023). "In other words, the amount of sIL-6R was lower compared to sgp130 in SLE and IgA patients, though we could consider the simultaneous activation of the two IL-6-mediated signaling pathways in SLE and IgA nephropathy." (PMID 34205600, 2021). "IL-6 increased 5.40 folds in SLE group (p < 0.01), respectively 5.78 folds in LN group (p < 0.01), when compared with control group and 1.58 folds when compared with IgA nephropathy group (p < 0.05)." (PMID 34205600, 2021). "IgG-ddIgA1 complexes from both patients with IgA nephropathy (IgAN-IgG-dd-IgA1) and healthy controls (HC-IgG-dd-IgA1) could induce the proliferation of mesangial cells and up-regulate expression of MCP-1, IL-6 and CXCL1." (PMID 28969604, 2017).
IgA nephropathy (continued). "Clinically, at least in our medical center, CRP and IL-6 are not routine examination items for patients with IgA nephropathy, and there is no guideline recommending routine examination of CRP and IL-6 in IgAN patients." (PMID 35664006, 2022).
left ventricular hypertrophy (22 papers, 2016 to 2025). Enlargement of the LEFT VENTRICLE of the heart. "For example, interleukin-6 (IL-6) was found to be associated with left-ventricular hypertrophy and systolic dysfunction in patients with CKD, and a high level of IL-6 in CKD contributed to chronic inflammation and subsequently left-ventricular dysfunction." (PMID 36231037, 2022). "In this study, serum IL-6 levels seemed to be associated with left ventricular hypertrophy and presence of atherosclerotic carotid plaques." (PMID 28747175, 2017). "Genetically predicted BMI is associated with higher left ventricular hypertrophy and increased concentrations of triglycerides, glucose, insulin, and interleukin 6 (an inflammatory marker), which may contribute to the observed associations with CVD." (PMID 31195408, 2020). "Adding to these findings, studies in IL-6 knockout mice demonstrated reduced left ventricular hypertrophy in response to pressure overload induced by transverse aortic constriction compared to wild-type mice." (PMID 41196450, 2025). "In CKD patients, elevated levels of IL-6 and TNF-α have been linked to left ventricular hypertrophy, arterial stiffness, and increased cardiovascular mortality." (PMID 41011058, 2025). "IL-6 deletion attenuates left ventricular hypertrophy and dysfunction induced by pressure overload, indicating IL-6 signaling is essential cardiac myocytes hypertrophy." (PMID 39411175, 2024). "Elevated plasma levels of C-reactive protein and interleukin 6 (IL-6) correlate with left ventricular hypertrophy (LVH) and contractile dysfunction in CKD patients." (PMID 36769308, 2023). "IL-6 is a strong inducer of STAT3 and by inference STAT3 was implicated in left ventricular hypertrophy and dysfunction in this study." (PMID 27899891, 2016). "Furthermore, studies in rats where IL-6 infusions have been performed showed reinforced development of concentric left ventricular hypertrophy and ventricular stiffness." (PMID 41196450, 2025). "Some scholars had found that deletion of IL-6 might attenuate pressure overload-induced left ventricular hypertrophy and dysfunction." (PMID 32595726, 2020). "IL-6 gene deletion inhibits angiotensin II- or transverse aortic constriction- (TAC-) induced hypertensive cardiac hypertrophy, while IL-6 infusion causes left ventricular hypertrophy independent of blood pressure." (PMID 32831633, 2020).
lipid metabolism disorders (22 papers, 2015 to 2025). "Elevated pro-inflammatory cytokines such as TNF-α and IL-6 have been linked to lipid metabolic disorders, while oxidative stress biomarkers including GSH, CAT, SOD, and MDA are widely recognized indicators of redox homeostasis." (PMID 41304686, 2025). "Therefore, the decreased IL-6 levels in the present study may be related to lipid metabolism disorders caused by PS-MPs." (PMID 38799170, 2024). "Transcriptomic analysis suggested that reducing IL-6 levels potentially played a critical role in the EWP-mediated alleviation of lipid metabolism disorders." (PMID 40647090, 2025). "Hepatic IL-6 levels were only slightly decreased in Mg-restricted mice, but this may also indicate a hepatic inflammatory response to Mg-restriction, finally leading to oxidative stress as well as lipid metabolism disorders." (PMID 34822420, 2021). "ALT, AST, IL-6, TNF-a, TC, TG, and FFAs levels significantly increased in the serum and liver tissues of cPtenf/fPck1f/f mice, suggesting more serious liver injury and lipid metabolism disorder in cPtenf/fPck1f/f mice." (PMID 36918564, 2023).
mesothelioma (22 papers, 1998 to 2025). A usually malignant and aggressive neoplasm of the mesothelium which is often associated with exposure to asbestos. "Mesothelioma cells produce IL-6, and an elevation of the circulating level of IL-6 has been already described in mesothelioma patients, with this increase being associated with a negative clinical condition." (PMID 37626858, 2023). "Interleukin 6 has been implicated as one of the possible soluble factors responsible for the increase in platelet count seen in mesothelioma patients." (PMID 11875694, 2002). "Chronic inflammatory states may promote mesothelioma development via persistent cytokine signaling – particularly IL-6, which is also implicated in the tumor microenvironment of prostate, renal and gynecologic malignancies." (PMID 41409117, 2025). "Mesothelioma cells, orchestrate the release of macrophage-attractant factors such as interleukin (IL)-8, IL-6, C-C motif chemokine ligand 2 (CCL2/MCP-1), G-CSF, GM-CSF, and MIP-1α, key players in sustaining tumor growth." (PMID 40016284, 2025). "In parallel with clinical studies, we demonstrated in the murine TI model of surgical inflammation that intratumoral IL-6 is significantly increased in AB12 mesothelioma flank tumors that undergo a surgical insult as compared with untreated control tumors." (PMID 40331601, 2025). "Monoclonal antibodies raised against IL-6 are able to block the clinical symptoms in in vivo mesothelioma mouse models." (PMID 37626858, 2023). "Another study revealed that mesothelioma cells produce transforming growth factor-β via interleukin 6 after fibrin deposition and that mesothelioma cells become the main body of adhesive formation by transforming growth factor-β." (PMID 37733702, 2023). "The present study confirms earlier reports of high IL-6 in mesothelioma PE and of IL-6 plus IL-6Rα in NSCLC PE." (PMID 31741710, 2019). "For example, TGF-β and IL-6 are consistent features of the mesothelioma secretome and are cardinal activating molecules for fibroblasts." (PMID 31867277, 2019). "It is possible that treatment decreases interleukin 6 produced by the mesothelioma with a resulting decrease in the platelet count." (PMID 11875694, 2002). "The level of IL-6 in the pleural fluid of patients with mesothelioma was significantly higher than in the pleural fluid of patients with adenocarcinoma, and was about 60-1400 times higher than in the serum." (PMID 9528833, 1998). "As a pivotal mediator of innate immunity, IL-6 suppresses adaptive immune responses within the peritoneum, creating a maladaptive immune environment that enables evasion by tumor cells in peritoneal cancer and mesothelioma." (PMID 38689325, 2024). "Finally, we review the prospects for targeting the IL-6 pathway in the treatment of PC, focusing on common sites of origin, including ovarian, gastric, pancreatic, colorectal and appendiceal cancer, and mesothelioma." (PMID 38689325, 2024). "Indeed, our mesothelioma surgery/PDT trial reveals high circulating IL6 levels at the conclusion of macroscopic complete resection and was reproduced in mice using the TI model." (PMID 37700795, 2023). "Several inflammatory cytokines such as interleukin 6, tumor necrosis factor-β, and vascular endothelial growth factor could induce tumor growth of mesothelioma." (PMID 36139517, 2022). "However, in mesothelioma, the high serum level of IL6 has been indicated as a poor prognostic factor." (PMID 34201002, 2021). "Our published findings in NSCLC, mesothelioma and ovarian MPE reveal a profound degree of polarization dominated by near nM concentrations of IL-6/sIL6Rα, IL-8, IL10, VEGF, FGF2 and CXCL10." (PMID 37063842, 2023). "Regarding interleukin 6 (IL6), it has been reported that this cytokine is present in high concentration in the sera of patients with different cancers including mesothelioma." (PMID 34201002, 2021).
mesothelioma (continued). "The combination of IL-6 and IL-6Rα has been shown to drive VEGF production in mesothelioma cells; in the present study VEGF was significantly elevated in malignant PE as compared to benign PE, suggesting a contribution by tumor cells." (PMID 31741710, 2019). "Some authors have defined that, in mesothelioma cells, IL-6 is not able to induce tumor growth and anti-IL-6 therapy does not induce significant results in terms of reducing cancer growth." (PMID 37626858, 2023). "In animal models, ZA reduces the expression of a number of pro-inflammatory and angiogenic mediators, including VEGF, IL-6 and MCP-1 and an observational study in mesothelioma found falling levels of circulating VEGF to be a good prognostic factor after 8 weeks of chemotherapy." (PMID 25781025, 2015). "Thus, despite other malignancies where there is a clear correlation between IL-6 concentrations and poor prognostic factors, such a role in mesothelioma has not been defined." (PMID 37626858, 2023).